PNMA5 (PNMA family member 5)
Synonyms: KIAA1934
Tractability: PROTAC: ubiquitination databases record sites on it.
Gene: Protein-coding gene on chromosome X (152,988,824 to 152,994,116, reverse strand). Ensembl gene ENSG00000198883.
Subcellular location: Nucleus
Subcellular location (Human Protein Atlas): Centrosome
Gene Ontology:
Molecular function: identical protein binding; protein binding
Biological process: positive regulation of apoptotic process
Cellular component: nucleus
Homologues: Orthologues: chimpanzee PNMA5 (98% identical), macaque PNMA5 (94% identical), pig PNMA5 (67% identical), rat Pnma5 (57% identical), mouse Pnma5 (55% identical). Paralogues in human: PNMA3 (42% identical), PNMA2 (36% identical), PNMA1 (36% identical), MOAP1 (35% identical), PNMA6A (35% identical), PNMA6E (32% identical), PNMA6F (31% identical), ZCCHC18 (21% identical), ZCCHC12 (21% identical), PNMA8A (20% identical), PNMA8B (15% identical), PNMA8C (14% identical), and 1 more.
Diseases named in the same sentence as PNMA5 in open-access papers:
PNMA5 is named in the same sentence as 18 diseases in open-access papers, as found by Europe PMC text mining. Sharing a sentence is not in itself a finding about the gene and the disease. The quoted sentences say what the papers report.
breast carcinoma (3 papers, 2021 to 2024). "PNMA5 has an oncogenic effect in human breast cancer and cervical cancer cell lines, and studies have indicated its role in promoting bone metastasis of non-small-cell lung cancer." (PMID 38608077, 2024). "PNMA5 plays an oncogene effect in human breast cancer and cervical cancer cell lines, can promote cancer cell apoptosis and enhance chemosensitivity." (PMID 37576398, 2023). "Although, functions of Pnma5 in cancer progression had been partially revealed in colon cancer and breast cancer, the roles of Pnma5 playing in NSCLC bone metastases were still unclear." (PMID 34136487, 2021).
colon cancer (3 papers, 2019 to 2023). "High-throughput sequencing analysis reveals that PNMA5 may be associated with metastasis of colon cancer." (PMID 34136487, 2021). "Further studies are still needed to explore the biological functions and underlying molecular mechanisms of REG1B, TGM6, NTF4, PNMA5, and HOXC13 in colon cancer." (PMID 30884206, 2019). "The prognostic signature based on REG1B, TGM6, NTF4, PNMA5, and HOXC13 could divide colon cancer patients into high–risk and low–risk groups, with an AUC of the ROC of 0.771." (PMID 30884206, 2019). "Using these data, we constructed a prognostic signature based on the expression of REG1B, TGM6, NTF4, PNMA5, and HOXC13 which could provide great significant prognostic value for colon cancer." (PMID 30884206, 2019). "We then constructed a prognostic signature based on the expression of REG1B, TGM6, NTF4, PNMA5, and HOXC13 which could provide significant prognostic value for colon cancer." (PMID 30884206, 2019).
bone tumors (1 paper, 2021). "We examined the mRNA levels of Pnma5 in four metastatic bone tumors, one metastatic lung tumor and parental cells by quantitative real-time PCR." (PMID 34136487, 2021).
colorectal cancer (1 paper, 2023). A primary or metastatic malignant neoplasm that affects the colon or rectum. "Our RNA-Seq analysis also found that 5’-Aza-CdR exposure resulted in overexpression of multiple CT antigens in gastric cancer and colorectal cancer, including SSX1, TKTL1, SPANXB1, PNMA5, PNMA6E, GAGE12J, and PRSS56." (PMID 37400936, 2023).
Lewis Lung Carcinoma (1 paper, 2021). "In this project, we find that the expression of Pnma5 is higher in metastatic bone tumors of Lewis lung carcinoma than in metastatic lung tumors and parental Lewis lung cells." (PMID 34136487, 2021). "Altogether, BMP2 signaling was observed to enhance bone metastases of Lewis lung carcinoma via PNMA5 in vivo." (PMID 34136487, 2021). "Besides, the protein levels of Pnma5 were also increased in metastatic bone tumors of Lewis lung carcinoma in contrast with metastatic lung tumors." (PMID 34136487, 2021).
neuroblastoma (1 paper, 2017). Neuroblastoma (NB) is the most common solid, extracranial childhood tumor. "These assays using cultured neuroblastoma cells revealed that MBD4 does indeed control PNMA5 gene expression by binding to the methylated site of the PNMA5 promoter." (PMID 27706918, 2017).
cancer (5 papers, 2021 to 2024). A tumor composed of atypical neoplastic, often pleomorphic cells that invade other tissues. "Moreover, PNMA5 has been reported to promote apoptosis in human cancers." (PMID 34136487, 2021). "However, there is still no direct evidence to show that PNMA5 contributes to cancer metastases." (PMID 34136487, 2021).
tumor (5 papers, 2019 to 2024). "Overexpression of PNMA5 in NSCLC cells promoted the tumor-induced osteoclast differentiation of macrophages." (PMID 34136487, 2021). "Besides, high expression of PNMA5 enhances tumor-induced osteoclasts differentiation in vitro and promotes bone metastatic lesions formation in vivo." (PMID 34136487, 2021). "These contain known cancer-testis antigen genes (MEGA5, MEGA1, TEX15, PNMA5 and ROR1) and a number of new candidate genes (PAX2, NTN4, NTNG2 and PDE10A), these genes can be used as tumour markers or potential therapeutic targets with some clinical value." (PMID 37994961, 2023). "Pnma5 overexpression not only can promote cell migration and invasion of NSCLC cells but also tumor-induced osteoclasts differentiation." (PMID 34136487, 2021). "Among them were known cancer/testis antigen genes (PNMA5, SPATA22, ROR1, and CT45A6) and some new candidates (PAX2, HES4, PEG10, NTN4, PDE10A, and POSTN), these genes could be useful tumor markers and potential therapeutic targets." (PMID 30922328, 2019).
neurological disorders (1 paper, 2017). "Although other members have been found to be involved in paraneoplastic neurological disorders, death receptor-dependent apoptosis, and tumorigenesis, Pnma5 was thought to be a female fertility factor, as indicated by one genome-wide study." (PMID 29228573, 2017).
PNMA5 also shares sentences with these, for which no sentence is quoted: cervical cancer (2 papers); non-small cell lung carcinoma (2); bone metastasis (1); gastric cancer (1); glioblastoma (1); oral cancer (1); periodontitis (1); prostate carcinoma (1); thyroid cancer (1).